CYP4Z1 (cytochrome P450 family 4 subfamily Z member 1)
Diseases named in the same sentence as CYP4Z1 in open-access papers (continued):
Sharing a sentence is not in itself a finding about the gene and the disease.
tumor (24 papers, 2017 to 2026). "CYP4Z1, which showed the highest overexpression, has previously been linked to tamoxifen resistance and increased tumor growth in BC." (PMID 39997761, 2025). "There were significant associations between CYP4Z1 expression and pathological subtype, tumor stage, and tumor depth of invasion." (PMID 36143940, 2022). "Data analysis revealed a significant association between CYP4Z1 expression and pathological subtype, histological stage, and tumor depth of invasion (p < 0.05)." (PMID 36143940, 2022). "The high expression and poor prognosis association of CYP4Z1 prompted both in vitro and in vivo studies to unravel the enzyme’s contribution to tumour development." (PMID 34590601, 2021). "Although many studies demonstrated the aberrant expression of CYP4Z1 in many tumours, including in the breast, ovary and prostate the CYP4Z1 enzyme association with other tumours remains at the forefront of current research." (PMID 33692504, 2021). "CYP4Z1 expression was found to be significantly associated with tumour pathological subtype, tumour stage, tumour invasion, and lymph node metastasis (p < 0.05)." (PMID 34590601, 2021). "CYP4Z1 expression was strongly associated with increasing tumour histological grades." (PMID 33144882, 2020). "The results indicated that CYP4V2, CYP4X1, and CYP4Z1 expression were correlated with a higher tumor grade." (PMID 40723371, 2025). "Comparative genomic analysis shows that tumor-specific expressed sequences like CYP4Z1 are either evolutionarily new (primates or humans) or relatively young (mammals)." (PMID 41020804, 2025). "Later, it was shown that increased expression of CYP4Z1 promotes tumor angiogenesis and growth in human BC and that CYP4Z2P 3′-UTR is involved in promoting BC angiogenesis through the VEGF/VEGFR2 pathway." (PMID 38525735, 2024). "Heterogeneous CYP4Z1 expression was observed mainly in tumor regions, but this is likely because it was specifically higher in sample v2 which lacked any annotation of clearly normal regions." (PMID 35906899, 2023). "CYP4Z1 was reported to strongly promote tumor growth, metastasis, and neovascularization in cell lines and animal models." (PMID 38001897, 2023). "Compared to control cells, CYP4Z1 overexpression in tumor cells increased the expression levels of vascular endothelial growth factor A (VEGF-A) and suppressed the expression levels of tissue inhibitors of metalloproteinases 2 (TIMP-2)." (PMID 38001897, 2023). "Significantly high CYP4Z1 expression was found in patients with advanced stages of disease and tumor depth of invasion." (PMID 36143940, 2022). "By using in vitro and in vivo models, CYP4Z1 expression was found to significantly enhance tumor proliferation, tumor angiogenesis, and tumor metastasis." (PMID 36143940, 2022). "The first inhibitor identified was 1-benzylimidazole, which showed efficient blocking ability for production of 14, 15-EET in CYP4Z1 positive tumour cells relative to a poor inhibitory profile against other CYPs." (PMID 34590601, 2021). "CYP4Z1 was expressed in different tumour grades, but the expression increased gradually with the increasing of tumour grade." (PMID 33692504, 2021). "Our results are concordant with previous studies demonstrating high CYP4Z1 expression in tumours of the breast, ovary and prostate compared to normal tissues." (PMID 33692504, 2021). "Using cell lines models, CYP4Z1 expression enhanced tumour growth, angiogenesis and the spread of tumour cells in both in vitro and in vivo models." (PMID 33692504, 2021). "The multivariate analysis revealed that only CYP4Z1 expression and tumour stage were significantly correlated with patient survival (p < 0.05)." (PMID 34590601, 2021). "Further studies looking deeply into the mechanistic role of CYP4Z1 in tumour progression are also needed." (PMID 33144882, 2020). "Further studies, using larger sample sizes, are needed for better screening of CYP4Z1 expression in tumours." (PMID 33144882, 2020).
tumor (continued). "Here, CYP4Z1 was found to be highly expressed in malignant tumours when compared to corresponding normal tissues and benign tumours." (PMID 33144882, 2020). "In an attempt to investigate the mechanistic role of CYP4Z1 in tumour progression, several studies have demonstrated an overexpression of CYP4Z1 in cell line models and human tumour xenografts." (PMID 33144882, 2020). "The data presented support and extend previous investigations in which the overexpression of CYP4Z1 was displayed in many human tumours." (PMID 33144882, 2020). "There was a significant relationship between CYP4Z1 expression and histological type of tumour (p < 0.05)." (PMID 33144882, 2020). "In this study, for the first time, we present convincing evidence of CYP4Z1 expression in many tumours other than cancers of breast, ovary, prostate and colon, and we demonstrate the general absence of expression in the corresponding normal tissues." (PMID 33144882, 2020). "The results showed that CYP4V2, CYP4X1, and CYP4Z1 expression correlated with a higher tumor grade." (PMID 40723371, 2025). "At the same time, CYP4V2, CYP4X1, and CYP4Z1 showed correlation with the tumor grade." (PMID 41020804, 2025). "On the other hand, CYP4Z1 induction of ERα expression may affect tumorigenesis initiation; thus, its inhibition may prevent tumor development." (PMID 41020804, 2025). "Altogether, these findings provide significant evidence that CYP4Z1 may contribute to tumor progression and metastasis." (PMID 36143940, 2022). "Overall, CYP4Z1 biochemical activities towards arachidonic acid metabolism to either 20-HETE or 14,15-EET have been proposed as a causative mechanism contributing to tumour development." (PMID 34590601, 2021). "Taken as a whole, these findings may provide a plausible mechanism for CYP4Z1-driven tumour development." (PMID 34590601, 2021). "Additionally, a strong over-expression of CYP4Z1 was seen in metastatic tumour samples compared with primary tumours." (PMID 33692504, 2021). "Additionally, a high rate of CYP4Z1 expression was found in patients having tumour depth of invasion of T3 (100%, three) and T2 (97.4%, 37 cases), but not T1 (20.4%, 15 cases)." (PMID 34590601, 2021). "Importantly, CYP4Z1 expression significantly enhanced tumour growth, angiogenesis, and spread of cancer cells in both in vitro and in vivo models." (PMID 34590601, 2021). "Importantly, this CYP4Z1 differential expression between normal tissues and tumour tissues was significantly observed in many studies." (PMID 34590601, 2021). "Moreover, some degree of immunoreactivity was observed for CYP4Z1 in metastatic cancer tissues when compared to primary tumours." (PMID 33144882, 2020). "This confirms the hypothesis that CYP4Z1 is overexpressed in tumours and is, as such, a valid biomarker or drug target for the development of novel therapeutic strategies." (PMID 33144882, 2020). "CYP4Z1 was highly expressed in all tumours examined when compared to corresponding normal tissues." (PMID 33144882, 2020). "Additionally, we performed an in vivo tumorigenic assay with MDA-MB-231 cells after CYP4Z1- or CYP4Z2P-3′UTR knockdown and showed that the knockdown of CYP4Z1- or CYP4Z2P-3′UTR remarkably reduced the tumor-initiating potential of MDA-MB-231 cells." (PMID 30832689, 2019). "This may provide a possible molecular pathway for CYP4Z1-driven tumour progression." (PMID 34590601, 2021). "Interestingly, the rate of CYP4Z1 expression tended to increase with the tumour grade." (PMID 33144882, 2020). "Although all of the cell lines could form tumors at a density of 1 × 106 and 1 × 105 cells, CYP4Z1- or CYP4Z2P-3′UTR overexpressed cells showed increased tumor size and weight while knockdown of CYP4Z1- or CYP4Z2P-3′UTR decreased the tumor-initiating ability of MCF-7 cells." (PMID 30832689, 2019).
tumor (continued). "CYP4Z1 and CYP1B1 were highly expressed in malignant tissues compared to normal controls; expression correlated with higher tumor grade, suggesting their potential role as prognostic biomarkers for recurrence and therapeutic targets." (PMID 41404236, 2025). "Another investigation revealed that CYP4Z2P and its pseudogene, CYP4Z1-3′UTR, enhanced tumor neovascularization in breast cancer, presumably by activating the ERK1/2 and PI3K/Akt cascades." (PMID 38001897, 2023). "A positive correlation with increasing tumour grade has been observed with the expression of CYP4V2, CYP4X1 and CYP4Z1; while CYP1B1, CYP3A5 and CYP51 were significantly associated with the ER status of the tumour." (PMID 33809117, 2021). "One such possibility that has attracted considerable interest in tumour development and therapy is the only member of the CYP4Z subfamily (CYP4Z1)." (PMID 33144882, 2020). "We report that the CYP genes with highest expression, ranked by the mean expression in tumor tissues for all patients, are: CYP1B1 (mean normalized expression 112.8), CYP4Z1 (92.2), CYP2A6 (75.7), CYP4X1 (65.1), CYP4B1 (31.5), CYP2A7 (30.8), and CYP4F8 (11.6)." (PMID 28684774, 2017). "This suggests that other significantly altered transcripts such as RPS28, CYP4Z1, and IL6ST may represent novel biomarkers or candidate regulators of tumor progression." (PMID 35992327, 2022). "Further studies are required to look deeply into the mechanistic role of CYP4Z1 and CYP1B1 in tumour progression and to better validate whether they are druggable targets." (PMID 33692504, 2021). "Several reports indicate expression of CYP4Z1 and CYP1B1 in many tumours." (PMID 33692504, 2021). "The current study reveals, for the first time, an expression of CYP4Z1 in many different types of tumours with absence of the expression in corresponding normal tissues." (PMID 33144882, 2020). "CYP4Z1 positive tumours (82%) had a higher rate of lymph node metastasis than CYP4Z1 negative tumours (18%)." (PMID 33144882, 2020). "Furthermore, we revealed that CYP4Z1 and the pseudogene CYP4Z2P form a ceRNA network via competiting with several miRNAs, such as miR-211, miR-125a-3p, miR-197, miR-1226, and miR-204, here called ceRNET_CC, and both we and others have shown that these shared miRNAs exert tumor suppressive effects." (PMID 30832689, 2019).
cancer (14 papers, 2018 to 2025). A tumor composed of atypical neoplastic, often pleomorphic cells that invade other tissues. "Most of the orphan CYPs discussed in this review appear to be expressed in various cancer tissues, with only one, CYP4Z1, being specifically associated with the breast epithelium." (PMID 41020804, 2025). "Several studies have linked the CYP4Z1 expression with clinicopathologic features of different cancer patients." (PMID 33692504, 2021). "Importantly, CYP4Z1 expression was found to be associated with high-grade and late-stage disease and proved to be a poor prognostic marker for these cancers." (PMID 38001897, 2023). "One of the potential enzymes implicated in the progression of cancers is Cytochrome 4Z1 (CYP4Z1)." (PMID 36143940, 2022). "However, the CYP4Z1 enzyme’s association with cancer development remains the focus of current research." (PMID 34590601, 2021). "The aberrant expression of these enzymes in cancers has attracted researchers’ interest, particularly CYP4Z1." (PMID 36143940, 2022). "Knowledge in the field of the CYP4Z1 enzyme’s substrate recognition and catalytic properties is now quite valuable in the design and development of more selective cancer therapies." (PMID 34590601, 2021). "In these studies, CYP4Z1 was expressed at much higher levels in cancers of the breast, ovary, and prostate than in their corresponding normal tissues." (PMID 34590601, 2021). "While considered an interesting area of study, new and existing research opportunities emerge to unveil novel aspects of CYP4Z1 in cancer development and therapy." (PMID 34590601, 2021). "Several studies reported differential expression of CYP4Z1 in cancers of the breast, ovary, and prostate." (PMID 34590601, 2021). "The immunoreactivity for CYP4Z1 was shown to be positive in metastatic tissues of lymph node and ovary that were originally derived from primary carcinomas of breast and colon, respectively." (PMID 33144882, 2020). "Mutations of CYP4B1, CYP4Z1, and other CYP4 genes that generate 20-HETE are a potential risk for cancer." (PMID 31480463, 2019). "CYP4X1 is expressed in the brain and bronchial airways, while CYP4Z1 is expressed in mammary tissue; these proteins are also overexpressed in cancer compared to normal cells." (PMID 31480463, 2019). "Induction of CYP4 family members, including CYP4F2, CYP4F3, CYP4A11, and CYP4Z1, has been reported in various types of cancer." (PMID 31480463, 2019). "Interestingly, CYP4Z1 expression was found to stimulate the generation of CYP4Z1 autoantibodies in the sera of patients with cancers of the breast, lung, colon, prostate, and ovaries." (PMID 38001897, 2023). "Notably, CYP1B1, CYP2W1, CYP2J2, and, more recently, CYP4Z1 have been determined to have cancer-specific expression." (PMID 38001897, 2023). "Moreover, CYP4Z1 expression was found to enhance cancer cell stemness and tamoxifen drug resistance." (PMID 38001897, 2023). "Importantly, significantly high CYP4Z1 expres-sion was determined in patients with advanced-stage cancer and a high depth of invasion (p < 0.05)." (PMID 36143940, 2022). "This is an exciting field of study, as there are new and ongoing prospects for research that could reveal novel features of CYP4Z1 in the development and treatment of cancer." (PMID 36143940, 2022). "Of recent focus is the aberrant expression of CYP4Z1 in many cancers." (PMID 33692504, 2021). "As a result, CYP4Z1 was hypothesised to be a potential biomarker or drug target for the discovery and development of promising anti-cancer therapies." (PMID 33144882, 2020). "CYP4Z1 expression was also examined in several metastatic tissue specimens, such as liver, lung, ovary and lymph nodes, which were originally derived from primary carcinomas of colon, stomach, breast and squamous cell of lymph node, respectively." (PMID 33144882, 2020). "However, how CYP4Z1 is regulated in cancer is not well understood." (PMID 30071685, 2018).
cancer (continued). "Angiogenesis is a fundamental process in the growth and progression of tumors, and miR-197 promotes angiogenesis in cancer by increasing the VEGF-A/VEGFR2 pathway by binding to the CYP4Z2P and CYP4Z1 genes, and by activating the PI3K/pathways AKT and ERK1/2." (PMID 36143221, 2022). "Due to the latest success with CYP inhibitors as anti-cancer therapy, such as aromatase (CYP19) inhibitors, the potential to develop novel therapies may be offered by selective CYP4Z1 expression in certain cancers." (PMID 36143940, 2022). "Furthermore, CYP4Z1 overexpression promoted the expression of the vascular endothelial growth factor A (VEGF-A) and decreased the expression of the tissue inhibitor of metalloproteinases 2 (TIMP-2) in cancer cells compared to control cells." (PMID 36143940, 2022). "A bioinformatics method was then used to predict the transcriptional factors binding to the promoters of CYP4Z1 and the pseudogene CYP4Z2P, and transcriptional factor six2 attracted our attention based on its critical roles in organ development and promoting roles in cancers." (PMID 30832689, 2019).
CYP4Z1 also shares sentences with these, for which no sentence is quoted: adenocarcinoma (1 paper); benign tumours (1); breast adenoma (1); carcinomas of adrenal cortex (1); endometrial adenocarcinoma (1); invasive ductal carcinoma (1); invasive lobular carcinomas (1); lentivirus infection (1); lung carcinoma (1); melanoma (1); mucinous adenocarcinoma (1); oesophagus (1); ovarian disease (1); seminoma (1); Tremor (1); triple-negative breast carcinoma (1).